CHI3L1 (chitinase 3 like 1)
Diseases named in the same sentence as CHI3L1 in open-access papers (continued):
Sharing a sentence is not in itself a finding about the gene and the disease.
cancer (continued). "Here we showed that CHI3L1 promotes cancer cell proliferation by increasing the number of cells in the S stage." (PMID 30301907, 2018). "In this study, we show that CHI3L1 is commonly upregulated in the serum and cancer tissue of patients with GC." (PMID 30165890, 2018). "Western blots showed that the presence of CHI3L1 dramatically elevated the levels of c-Fos and c-Jun proteins in cancer cell nuclei, confirming the activation of the AP-1 family by CHI3L1." (PMID 28143526, 2017). "Confocal microscopy analysis demonstrated that CHI3L1 protein was co-localized with IL-13Rα2 on the plasma membrane of cancer cells." (PMID 28143526, 2017). "YKL-40 (also known as Chitinase 3-like 1) is a glycoprotein produced by inflammatory, cancer and stem cells." (PMID 29126445, 2017). "Protein phosphorylation and gene expression were performed to study the signaling pathway activation of cancer cells after CHI3L1 treatment." (PMID 28143526, 2017). "The angiogenic factor YKL-40 (human cartilage glycoprotein HC-gp39, CHI3L1) is produced by cancer cells, inflammatory cells, and stem cells." (PMID 29112161, 2017). "In this context, these findings showed that CHI3L1 promoted cancer cell metastasis by interacting with IL-13Rα2 on cancer cell membranes." (PMID 28143526, 2017). "The results of this study demonstrated that CHI3L1, which is secreted by M2 macrophages, promoted cancer metastasis by activating the IL-13 receptors of cancer cells." (PMID 28143526, 2017). "Further data indicated that the activation of the AP-1 family by CHI3L1 significantly upregulated the levels of MMP expression in cancer cells." (PMID 28143526, 2017). "The results showed that knockdown of IL-13Rα2 gene expression in cancer cells significantly reduced the CHI3L1-induced activation of AP-1 transcription factors and upregulation of MMP gene expression in cancer cells." (PMID 28143526, 2017). "When cancer cells were incubated with the recombinant CHI3L1 protein (rCHI3L1), the CHI3L1 protein bound IL-13Rα2, indicating an interaction between the two proteins." (PMID 28143526, 2017). "In the presence of isolated M2 macrophages, the number of adherent cancer cells was significantly reduced by the antibody compared with the controls, showing that CHI3L1 appeared to be required for cancer cell adhesion." (PMID 28143526, 2017). "The CHI3L1 protein functioned by interacting with interleukin-13 receptor α2 chain (IL-13Rα2) molecules on the plasma membranes of cancer cells." (PMID 28143526, 2017). "Taken together, these findings demonstrated that the IL-13Rα2 receptor activated the MAPK signaling pathway following CHI3L1 stimulation, thus promoting cancer cell metastasis." (PMID 28143526, 2017). "The results showed that silencing CHI3L1 expression in isolated M2 cells led to significant decreases of cancer cell migration, adhesion, and invasion compared with the control levels." (PMID 28143526, 2017). "A wealth of clinical evidence has also revealed that elevated serum levels of CHI3L1 in GBM are positively correlated with cancer invasiveness, radioresistance, recurrence, and reduced patient survival times." (PMID 27121858, 2016). "A wealth of clinical evidence has revealed that elevated serum levels of CHI3L1 in GBM are positively correlated with cancer invasiveness, radioresistance, recurrence, and reduced patient survival times." (PMID 27801851, 2016). "Chi3l1 is induced by a variety of cancers where it portends a poor prognosis and plays a key role in the generation of metastasis." (PMID 27198666, 2016). "CHI3L1 is located on chromosome 1q32.1, and the product, YKL-40, a 40-kDa glycoprotein, is secreted by numerous human cells such as cartilage, synovium, endothelial cells, inflammatory cells, and cancer cells." (PMID 27121858, 2016).
cancer (continued). "In summary, the CHI3L1 protein is expressed in many types of cancer cells and its highest plasma levels have been found in patients with metastatic disease, short recurrence/progression-free intervals, and low overall survival." (PMID 26425658, 2015). "Elevated serum levels of CHI3L1 have been correlated with poor prognosis and shorter survival of patients with cancer and inflammatory diseases." (PMID 26425658, 2015). "As a member of the chitinase-like proteins, CHI3L1 is highly conserved and is produced by a variety of cells such as macrophages, neutrophils, SMCs, cancer cells, and arthritic chondrocytes." (PMID 24729664, 2014). "CHI3L1-GST fusion protein significantly stimulated cancer cell proliferation compared with that of GST control protein." (PMID 23613996, 2013). "Chitinase-3-like-1 glycoprotein (aka BRP-39, YKL-40) is a secreted protein that is upregulated in various types of cancers, including breast." (PMID 24399973, 2013). "The findings revealed that CHI3L1 expression was upregulated in various cancers, mainly in PTC." (PMID 42001899, 2026). "Notably, CHI3L1 protein levels significantly increase in response to inflammatory diseases, cancers, and degenerative conditions, making it a potential prognostic marker." (PMID 39827337, 2025). "Elevated CHI3L1 expression is observed in various human cancers and corresponding animal models." (PMID 40643503, 2025). "CHI3L1 signaling via these receptors is often activated in distinct combinations depending on cell type and pathological context, and it serves as a key regulatory molecule in fibrosis, allergic inflammation, autoimmune diseases, and cancer." (PMID 40643503, 2025). "Previous reports on multiple cellular targets of CLPs, and especially CHI3L1, in the context of cancer could further explain the immune cell changes observed in our mouse models upon chitin-mediated CLP blockade." (PMID 38605414, 2024). "Therefore, CHI3L1 protein is a target for precision medicine, and recent studies show a broad anti-cancer spectrum of CHI3L1 inhibition." (PMID 39399677, 2024). "Elevated serum CHI3L1 levels are biomarkers of poor prognosis in patients with advanced cancers." (PMID 39026176, 2024). "In the context of cancer, CAFs have been shown to facilitate the migration of monocytes, leading to their transition towards the M2 phenotype through the secretion of factors such as chitinase 3-like 1 (Chi3L1)." (PMID 39655080, 2024). "It is expected that it could also contribute to the treatment of not only inflammation but also cancer by inhibiting CHI3L1 expression in multiple ways including anti-CHI3L1 specific antibodies, methylxanthine derivatives, and chitin microparticles." (PMID 38667293, 2024). "However, more preclinical and clinical studies are necessary to assess the safety, efficacy, and long-term effects of CHI3L1(YKL40)-targeted therapies in cancer patients." (PMID 38543093, 2024). "Furthermore, we have utilized platforms like STRING to identify potential target proteins for CHI3L1 in various inflammatory diseases and cancer." (PMID 38177294, 2024). "The glycoprotein YKL-40, also known as chitinase-3-like protein 1 (CHI3L1), is detected primarily in various cell types, including macrophages, chondrocytes, fibroblasts, vascular smooth muscle cells, endothelial cells, and even certain cancer cells." (PMID 39080712, 2024). "Additionally, we summarize the potential binding sites of CHI3L1 involved in regulating the cell cycle to promote cancer and its role as a messenger to activate multiple downstream signaling pathways." (PMID 39068486, 2024). "TAMs‐secreted chitinase 3‐like protein 1 (CHI3L1), which is a glycoprotein highly expressed on cancer cells, promotes gastric and breast cancer metastasis by interacting and activating the interleukin‐13 receptor α2 chain (IL‐13Rα2) molecules present on cancer cells." (PMID 38703051, 2024).
cancer (continued). "CHI3L1(YKL40) inhibition can alter signaling transduction and oncogenic processes, attenuate immune checkpoint gene expression, and suppress angiogenic and metastatic properties to inhibit cancer progression." (PMID 38543093, 2024). "Overall, CHI3L1(YKL40) plays a significant role in cancer development and progression." (PMID 38543093, 2024). "To investigate whether CHI3L1-induced autophagy by JNK activation affects cancer cell proliferation, we performed MTT assay." (PMID 37340009, 2023). "Additionally, CHI3L1 overexpression promoted the formation of autophagosomes in various cancer cell lines: it also increased the co-localization of LC3 and the lysosome marker protein LAMP-1, indicating an increase in the production of autolysosomes." (PMID 37340009, 2023). "In addition, apoptosis in cells transfected with CHI3L1 siRNA and treated with thapsigargin was significantly increased in cancer cells (27.50±4.37%)." (PMID 37215572, 2023). "CHI3L1 is closely related to the molecular mechanisms of cancer cell migration, growth, and death." (PMID 37340009, 2023). "Moreover, CHI3L1 is also involved in processes of systemic inflammation, such as autoimmune diseases, cancers, liver diseases, and diabetes." (PMID 36983366, 2023). "This indicates that the methylation status of the MGMT promoter might influence CHI3L1's function in human cancers." (PMID 37902124, 2023). "However, due to the variability of inducers, the complexity of the cancer environment, and the variability of the disease, it is difficult to summarize the role of the CHI3L1 protein in different cancers." (PMID 38003338, 2023). "YKL‐40, also known as chitinase 3‐like 1 protein, stimulates angiogenesis, cell proliferation and differentiation, re‐modulates extracellular matrix, activates Akt signalling, protects against apoptosis and promotes metastases and cancer progression." (PMID 36440611, 2023). "Therefore, the following subsections elaborate and summarize several studies involving CHI3L1 and various cancers and macrophages." (PMID 38003338, 2023). "The depletion of CHI3L1 increased the proportion of apoptotic cancer cells." (PMID 37215572, 2023). "In addition to directly affecting cancer progression, CHI3L1 also acts as an intermediate protein involved in the regulation of other proteins in cancer." (PMID 38003338, 2023). "Recent studies have also shown the important role of CHI3L1 in cellular proliferation, macrophage survival, inflammatory cell recruitment and differentiation, tissue remodeling, angiogenesis, and cancer metastasis." (PMID 37166517, 2023). "CHI3L1 is overexpressed in many human cancers including GBM." (PMID 37511403, 2023). "Moreover, a higher serum CHI3L1 level has shown promise as a valuable prognostic biomarker in different cancers." (PMID 37902124, 2023). "This blocking of the CHI3L1‐IL‐13Rα2 signal caused the inhibition of c‐Jun N‐terminal kinase (JNK)‐activator protein 1 (AP‐1) signals, resulting in the prevention of lung metastasis and cancer cell growth." (PMID 34758182, 2022). "Recent studies indicated that Chi3L1 is critical for cancer development and metastasis." (PMID 34861103, 2022). "The secretory mode of CHI3L1 makes it a promising target for cancer treatment." (PMID 34987649, 2022). "CHI3L1 specifically binds to IL‐13Rα2 in cancer cells, thus promoting cancer growth." (PMID 34758182, 2022). "The suppressive effect of K284 on the CHI3L1/IL‐13Rα2 interaction could inhibit cancer cell growth‐related downstream signals." (PMID 34758182, 2022). "To investigate whether K284 inhibits CHI3L1 signaling in cancer cell growth, we first analyzed the possibility of the physical interaction between CHI3L1 and K284 in silico." (PMID 34758182, 2022). "Our previous studies indicated that Chi3L1 is critical for cancer development and metastasis." (PMID 34861103, 2022).
cancer (continued). "To investigate the binding effect of K284 to CHI3L1, we questioned whether the binding affinity is conversely related to the inhibitory effect of K284 on cancer cell." (PMID 34758182, 2022). "CHI3L1 was found to be over-expressed in cancer lesions than in the normal adjacent tissues." (PMID 36276655, 2022). "In addition, the secretory mode of CHI3L1 makes it a promising target for cancer treatment as shown by several chemical inhibitors of CHI3L1 17, 18 and neutralizing antibodies 19, 20 developed." (PMID 34987649, 2022). "A growing body of evidence substantiates the roles of CHI3L1 in cancer development." (PMID 34612767, 2021). "Recently, chitinase 3 like 1 (Chi3L1) expression has been found in a variety of cancer cells." (PMID 31929760, 2020). "These indicated that CHI3L1 was mainly involved in the process of cancer metastasis." (PMID 30165890, 2018). "CHI3L1 is secreted by primary immune cells, endothelial cells, inflammatory cells and cancer cells." (PMID 30301907, 2018). "We further showed that overexpression of CHI3L1 significantly increased the number of cells in S stage and decreased the number of cells in G0/G1 stage in both HepG2 and Bel7404, suggesting that CHI3L1 promoted cancer cell proliferation by regulating cell cycles." (PMID 30301907, 2018). "The mouse model was used to validate the function of CHI3L1 in cancer metastasis in vivo." (PMID 28143526, 2017). "Furthermore, this was also evident for CHI3L1, a glycoprotein secreted by activated macrophages and upregulated in many inflammatory conditions, such as cancer, cardiovascular diseases, and neurodegenerative diseases." (PMID 28878732, 2017). "The luciferase reporter assays showed that AP-1 transcriptional activity in cancer cells was significantly increased by the addition of rCHI3L1 protein compared with the control, indicating that AP-1 transcriptional activity was activated by CHI3L1 protein." (PMID 28143526, 2017). "Studies have found possible biological functions and mechanisms for CHI3L1 in cancer cells." (PMID 26452028, 2015). "CHI3L1 was found to promote cancer cell proliferation, macrophage recruitment and angiogenesis." (PMID 26425658, 2015). "CHI3L1 is known to play a role in cancer and chronic inflammation." (PMID 24116216, 2013). "Chitin microparticles may represent one possible method to neutralize the adverse effects of endogenous CHI3L1 on cancer cell growth, particularly in an inflammatory tissue environment." (PMID 24399973, 2013). "Given that CHI3L1 is overexpressed in many human cancer cells, we addressed the question of whether CHI3L1 possesses transforming properties on 293 cells, one of the most common cell types used in molecular biology research." (PMID 23675241, 2011). "The role of CHI3L1 in cancer is unknown, but it has been suggested that it has a function in a number of pro-survival processes." (PMID 18781180, 2008). "Studies have revealed that CHI3L1 could contribute to other cancer types." (PMID 40821115, 2025). "Therefore, when assessing CHI3L1’s role of the efficacy of therapeutic interventions, it is essential to account for these limitations and compliment animal studies using huma cells, tissues (e.g., cancer cell lines), and clinical specimens." (PMID 40643503, 2025). "In addition, CHI3L1 binds to a receptor complex consisting of TMEM219 and CD44v3, activating pathways like AKT, MAPK (p42/p44), and β-catenin, thereby promoting tumorigenesis, particularly in cancer cells and cancer-associated fibroblasts." (PMID 40643503, 2025). "Notably, CHI3L1 is a promising therapeutic target in cancer." (PMID 38835347, 2024). "Intriguingly, previous studies have revealed that CHI3L1 could regulate various biological and cellular processes, including angiogenesis, inflammation, tissue remodeling, and is involved in the development of cancers 8-11." (PMID 39513118, 2024). "In addition to its role in cancer cells, CHI3L1 also has regulatory abilities in immune cells." (PMID 37958973, 2023).
cancer (continued). "Also, according to the literature, IL-8 (Interleukin-8) and VEGFA (vascular endothelial growth factor) angiogenic properties may be influenced by CHI3L1 to promote cancer progression." (PMID 37046579, 2023). "However, 4-PBA prevented the reduction of cancer cell proliferation by the depletion of CHI3L1." (PMID 37215572, 2023). "However, the physiological and pathophysiological roles of CHI3L1 in the development of metabolic and neurodegenerative diseases and cancer remain unclear." (PMID 38003338, 2023). "However, the depletion of CHI3L1 increased the phosphorylation of PERK in cancer cells." (PMID 37215572, 2023). "Notably, recent research highlighted the dual nature of CHI3L1 in cancer." (PMID 37902124, 2023). "Therefore, CHI3L1 represents an attractive therapeutic target and biomarker predicting resistance to anti-PD-1/PD-L1 therapy and warrants further investigation to benefit patients with different types of cancer." (PMID 34987649, 2022). "Non-enzymatic CHI3L1 is highly expressed in various cancer types, such as lung 15, colon, gastric, and breast cancers 16, and is associated with low survival rates of patients with cancer." (PMID 36276655, 2022). "Therefore, we interrogated whether plasma level of CHI3L1 correlated with prognosis of cancer patients." (PMID 34987649, 2022). "Additionally, the expression of CHI3L1 and IL‐13Rα2 was elevated in many cancers." (PMID 34758182, 2022). "CHI3L1 exerts pleiotropic effects which may be mediated via interaction with several receptors to regulate wide range of functions in immune responses and extracellular matrix assembly in chronic inflammations, neurodegenerative diseases and cancer." (PMID 34987649, 2022). "We previously found that Chi3L1 could be a significant new therapeutic cancer target." (PMID 34861103, 2022). "However, different MMPs were upregulated by CHI3L1 in different cancer cell types." (PMID 28143526, 2017). "Western blot data showed that the CHI3L1 protein was significantly upregulated in the isolated M2 macrophages and their culture supernatants compared with the isolated M1 macrophages, suggesting that the CHI3L1 protein might play important roles in promoting cancer cell metastasis." (PMID 28143526, 2017). "In addition, expression levels of cell cycle (CDK2, CDC2, CCND2) and inflammation markers linked to cancer (NOS2, TGFβ1, CHI3L1 and TFPI) were significantly increased in Caco-2WT/miR-373 compared with Caco-2WT/miR-c, but decreased in Caco-2D299G/α-miR-373 compared with Caco-2D299G/α-miR-c." (PMID 27271572, 2016). "Chi3l1/YKL-40/BRP-39 may play a particularly important role in cancer." (PMID 23972995, 2013). "Thus, understanding how molecules like CHI3L1, expressed in the target organ at “pre-metastatic” stages, can promote the establishment of cancer cells at these target sites, may provide insights about how to disrupt these mechanisms therapeutically." (PMID 24399973, 2013). "The Mφ-CM contained a number of EMT inducers, including CHI3L1, IL-10, IL-6, IL-8, and TNF-α, which are known to play a role in cancer metastasis, migration, invasion, chemotaxis, and endothelial cell junction retraction." (PMID 40678259, 2025). "Chitinase-3-like protein-1 (CHI3L1) or YKL40 is a secreted glycoprotein involved in inflammation, macrophage polarization, apoptosis, and cancer." (PMID 41294748, 2025). "CHI3L1 is primarily expressed in epithelial cells, followed by CAFs and myeloid cells, and IYD is specifically expressed in cancer epithelial cells, with minimal expression in other cells." (PMID 39512680, 2024). "For example,CHI3L1 inhibitors, including GM-CT-01 and ONO-7475, undergo clinical trials for the treatment of cancer." (PMID 38962736, 2024). "YKL40, the protein product of CHI3L1, is an inflammatory glycoprotein produced by various cell types, including cancer, immune, and connective tissue cells." (PMID 38543093, 2024).